TMPRSS2 (transmembrane serine protease 2)
Diseases named in the same sentence as TMPRSS2 in open-access papers (continued):
Sharing a sentence is not in itself a finding about the gene and the disease.
cancer (continued). "This review illustrates the complexity of therapeutically targeting ACE2 and TMPRSS2 due to their contrasting roles in cancer progression and viral entry." (PMID 40145441, 2025). "The link between TMPRSS2 expression and immune response-relevant profiles was further validated by in silico analyses of cancer genome databases with a positive correlation between TMPRSS2 and the expression of HLA-I APM and IFN type I and II pathway genes." (PMID 40055791, 2025). "The heightened gene expression of TMPRSS2 in these cancers suggests its potential as a biomarker and therapeutic target." (PMID 39858469, 2025). "The deletion of 21q22.3 is the result of the observed TMPRSS2–ERG fusion event, and the loss of the tumor suppressor gene PTEN at 10q23.31 is known as a key driving event in cancer." (PMID 39347576, 2024). "In this context, the PI3K/AKT pathway is activated and cooperates with TMPRSS2-ERG fusion to regulate the expression of genes involved in cancer initiation of neoplasia and proliferation as well as in EMT." (PMID 38674385, 2024). "TMPRSS2’s role in degrading extracellular matrix proteins facilitates cancer cell invasion and metastasis." (PMID 39350850, 2024). "TMPRSS2-ERG fusion serves as a cancer-specific biomarker for early PCa diagnosis and can be detected non-invasively in urine samples, thus potentially reducing overtreatment." (PMID 38674385, 2024). "We further validated that TMPRSS2 was downregulated with tumor progression in the LUAD cohort we collected from Jiangsu Cancer Hospital, China." (PMID 38862975, 2024). "TMPRSS2 is dysregulated in several types of malignant neoplasms, including breast, lung, gastric, ovarian, and renal carcinomas." (PMID 37511059, 2023). "It is well established that TMPRSS2 plays a role not only in infectious diseases but also in cancer progression." (PMID 37445653, 2023). "Another important aspect of the pathogenetic role of TMPRSS2 in cancer is its involvement in chromosomal rearrangements." (PMID 37511059, 2023). "Last, SLC6A20 was found to interactwith an ACE2 homologue protein TMEM27, and TMEM27 was upregulatedin different cancer types along with its being positively correlatedpredominantly with ACE2 and TMPRSS2, which are known SARS-CoV-2-associatedproteins." (PMID 37041751, 2023). "This genomic event results in the fusion of the ERG proto-oncogene with the androgen-driven promoter of the TMPRSS2, setting the transcription of the former under hormonal affection and resulting in its over-expression in cancer cells." (PMID 37185705, 2023). "In fact, their associations (SCARB1 most in all investigated 33 cancers, followed by NRP1 in 31 cancers, TMPRSS2 in 27 cancers, AXL in 25 cancers and ACE2 in 13 cancers) appeared in more cancer types than those of CNVs with the same trends among the five STGs." (PMID 36875081, 2023). "Another study used a bioinformatic approach to analyze the gene and protein expression data of coronavirus receptors (DPP4, ANPEP, ENPEP, TMPRSS2) in human normal and cancer tissues of different organs including kidneys." (PMID 38255667, 2023). "Before this, TMPRSS2 has presented biological functions in cancer, but the roles remain controversial and the mechanism remains unelucidated." (PMID 36992839, 2023). "There is no in-depth literature on this topic however some studies have shown that the expression of TMPRSS2 can be altered in various types of cancer." (PMID 38255667, 2023). "Kaplan–Meier plotter database was employed to verify the prognosis of TMPRSS2 in various types of cancer based on 7489 patient data." (PMID 34951103, 2022).
cancer (continued). "In the end, our study planned the genetic and epigenetic variation of TMPRSS2 in human malignant tumors for the first time and provided a relatively comprehensive understanding of the carcinogenic effects of TMPRSS2." (PMID 35281819, 2022). "According to cancer stage, significant downregulation of TMPRSS2 expression was observed in stage 1, 2, 3 and 4 LUAD and LUSC patients." (PMID 35017320, 2022). "In the end, our study planned the genetic and epigenetic variation of TMPRSS2 in human malignant tumors for the first time." (PMID 35281819, 2022). "In this study, the expression, genetic variations, correlated genes, immune infiltration and prognostic value of TMPRSS2 were analysed in many cancers using different bioinformatics platforms." (PMID 34951103, 2022). "The expression of TMPRSS2 is also related to the infiltration of cancer-related fibroblasts, and the potential pathways and functional mechanisms were analyzed through KEGG/GO enrichment." (PMID 35281819, 2022). "To study the relationship between TMPRSS2 copy number changes in different cancers and gene expression, we looked for genes that were coexpressed with TMPRSS2 and presented them in the form of a scatter plot sequentially." (PMID 35281819, 2022). "In protein network analysis, we determined 27 proteins as protein partners of TMPRSS2, which can regulate the progression and prognosis of cancer mediated by TMPRSS2." (PMID 34951103, 2022). "Further analysis of the expression of CTSL mutant showed a correlation with FURIN and TMPRSS2, suggesting a potential role of CTSL mutations in modulating SARS-CoV-2 entry in cancers." (PMID 35414771, 2022). "We explored the prognostic value of TMPRSS2 mRNA expression in many types of cancers by PrognoScan and Kaplan–Meier plotter databases." (PMID 34951103, 2022). "To explore TMPRSS2 expression in various cancers, we analyzed the mRNA expression levels of TMPRSS2 through the Oncomine database." (PMID 35558557, 2022). "Databases including Oncomine and TCGA were employed for the evaluation of TMPRSS2 differential expression patterns in many kinds of cancer by UALCAN and GEPIA." (PMID 34951103, 2022). "Among the 32 datasets, the percentage of TMPRSS2 alteration frequency varied from 0% to 42.7% in various cancers." (PMID 34951103, 2022). "We report that the mutant CTSL expression correlates with elevated FURIN expression in multiple cancers, while there is no such correlation in a few cancers (FURIN panel); but TMPRSS2 showed either increase or decrease in a few cancers (TMPRSS2 panel)." (PMID 35414771, 2022). "The TIMER, CIBERSORT, CIBERSORT-ABS, QUANTISEQ, XCELL, MCPCOUNTER, and EPIC algorithms were adopted to detect the potential relationship between different immune cell infiltration levels and TMPRSS2 gene expression in different cancer types." (PMID 35281819, 2022). "Our study comprehensively revealed the relationship between the prognosis of TMPRSS2 in pan-cancers and tumor immunity." (PMID 35558557, 2022). "In our study, the expression, promoter methylation, genetic variation, protein partners, associated genes, immune infiltration and prognostic value of TMPRSS2 were systematically analysed in many kinds of cancer in humans." (PMID 34951103, 2022). "Then, the mutations and CNAs were analysed in the 27 predicted protein‐related coding genes of TMPRSS2 via the cBioPortal database, the results showed that these genes were altered in 38% (3225/10,953) queried cancer patients." (PMID 34951103, 2022). "In order to further analyze the prognosis of TMPRSS2 in cancers, Kaplan-Meier plotter databases and GEPIA databases were utilized." (PMID 35558557, 2022). "ADAM17 mRNA levels were lower than HSPA5 and FURIN but higher than ACE2 and TMPRSS2 in most cancer types." (PMID 35720350, 2022). "Here, we found an overall upregulated expression pattern of CXCL10 and TMPRSS2 compared to a normal state depending on the individual stages of cancer and different age groups." (PMID 36239108, 2022).
cancer (continued). "In this study, we analyzed the mRNA expression of TMPRSS2 in various cancers in Oncomine and TIMER databases." (PMID 35558557, 2022). "The corresponding heatmap data also indicated the correlation between TMPRSS2 and the top 10 genes in most detailed cancer types." (PMID 35281819, 2022). "TMPRSS2:ERG-positive disease appears to be particularly sensitive to the anti-cancer effects of tomato sauce." (PMID 36501182, 2022). "TMPRSS2, a membrane-bound serine protease, is known to overexpress in the early stages of cancer and increase the severity of pain in these patients." (PMID 36474139, 2022). "Human cancer cell lines were screened for the SARS-CoV-2 cellular entry factors ACE2 and TMPRSS2 based on RNA-seq data of the Cancer Cell Line Encyclopedia (CCLE)." (PMID 34339474, 2021). "Several studies have shown the lower prevalence of TMPRSS2/ERG gene fusion/ERG‐overexpression in TZ cancer cases." (PMID 35475132, 2021). "The top cancers expressing TMPRSS2 were also from the gastrointestinal (colon, stomach, pancreas, and esophagus) and genitourinary (prostate) tracts." (PMID 33633121, 2021). "We observed that ACE2 and TMPRSS2 had a lower expression level across all cancer types, compared to other SARS-CoV-2-required genes." (PMID 35082790, 2021). "We conducted a pan-cancer analysis of ACE2 and TMPRSS2 across 31 types of tumors in TCGA pan-cancer datasets." (PMID 34257580, 2021). "The role of TMPRSS2 in the pathogenesis of cancer and various infectious diseases of viral origin has led to several attempts to inhibit its activity as a way of preventing and treating disease progression." (PMID 34336361, 2021). "We compared expression of ACE2 and TMPRSS2 in tumor and its normal control tissue in TCGA pan-cancer datasets using GEPIA2." (PMID 34257580, 2021). "Together, from these two datasets, it appears that ACE2/TMPRSS2 have transient elevation with cancer treatments that resolve in less than 20 days post-treatment, while CTSL exhibits a prolonged elevation at for at least 4–6 weeks post-treatment." (PMID 33633121, 2021). "TMPRSS2 functions as a host factor for some viruses 12, 13 and involves signal transduction between cancer cells and the extracellular environment." (PMID 34131396, 2021). "The susceptibility and symptoms of different cancer patients were systematically assessed by analyzing abnormal expression of ACE2 and TMPRSS2." (PMID 34257580, 2021). "Our data also highlight alveolar and malignant subsets that express the serine proteases TMPRSS2 and TMPRSS4 implicated in lung pathobiology, including cancer, which also act as SARS-CoV-2 coreceptors." (PMID 33809063, 2021). "The central association marker, DPP4 positively correlated with ACE2 (normal: R 0.308; cancers: 0.382), TMPRSS2 (normal: R 0.524; cancers: 0.382) and FURIN (normal: R 0.498; cancers: R 0.246) in both datasets." (PMID 33796097, 2021). "A recent study reported that COVID-19 infection of host cells is facilitated by transmembrane protease serine 2 (TMPRSS2), angiotensin-converting enzyme 2, and other host cell proteases, such as cathepsin L, which is highly expressed in cancer patients." (PMID 33628602, 2021). "The prognostic relationship between NRP1 and TMPRSS2 expression level and cancers were further confirmed by analysis with GEPIA." (PMID 34168096, 2021). "Our data suggest that quinine exerts antiviral activity against SARS-CoV-2 with lower cytotoxicity as compared to H-CQN and CQN and that this antiviral effect occurs in several TMPRSS2+ human cancer cell lines." (PMID 33918670, 2021). "Based on the evidence that TMPRSS2 has a role to play in cancer metastasis, bromhexine was administered systemically to cancer patients to observe its effectiveness in reducing the metastasis." (PMID 34336361, 2021).
cancer (continued). "In conclusion, the TMPRSS2 gene is highly expressed in normal prostate tissues and increased significantly in PRAD cancer tumours, indicating the susceptibility for the SARS‐CoV‐2 infection and high severity of COVID‐19 symptoms." (PMID 33609069, 2021). "The high expression level of TMPRSS2 in the tumor and corresponding normal tissues in cancers was verified via the Oncomine database." (PMID 33193689, 2020). "This suggests an acquisition of ERG binding and (de)regulation of WNT2 expression in the cancer cells which acquire the TMPRSS2-ERG fusion." (PMID 31818883, 2020). "Cleaved forms of TMPRSS2 bind to protease-activated receptor 2 to induce Ca2+ influx, which regulates pain and allodynia in patients with cancers expressing TMPRSS2." (PMID 33142989, 2020). "Both oestrogen receptors (ERα and ERβ) are expressed on normal prostate cells but they would possibly mediate opposite effects at least in cancer, with up and down-regulation of TMPRSS2-ERG, respectively." (PMID 32774170, 2020). "Univariate analysis was performed through GEPIA to assess the impact of TMPRSS2 on various cancer survival rates." (PMID 33193689, 2020). "The TMPRSS2:ERG status was available from 6196 cancers (using ERG break apart FISH analysis) and from 11,521 cancers (using ERG-IHC) of all tumors with interpretable data on hnRNPA1." (PMID 32417965, 2020). "This TMPRSS2-ERG positive case had a somatic missense mutation in MED12 (c.3670C > G; p.Leu1224Val), that is potentially pathogenic in many cancers, including prostate, via its upregulation of Wnt/β-catenin signalling." (PMID 32392735, 2020). "The significant up-regulation of YAP1 in cancers having a TMPRSS2:ERG fusion is consistent with data showing that ERG can activate YAP1 dependent transcription and tumour development." (PMID 32488048, 2020). "The significant upregulation of PNUTS in cancers having a TMPRSS2:ERG fusion demonstrates that PNUTS is either directly or indirectly impacted by ERG expression." (PMID 32377272, 2020). "Here, the expression of five genes, known to encode coronavirus receptors/interactors (ACE2, TMPRSS2, CLEC4M, DPP4 and TMPRSS11D), was investigated in normal and cancer tissues, and their molecular relationships with clinical comorbidities were investigated." (PMID 32970391, 2020). "GSE55945 contained ‘normal’ (non-cancer) prostate samples and low-grade primary PCa characterized by the absence or presence of the TMPRSS2:ERG fusion gene." (PMID 30733525, 2019). "In total, 51% (43/85) of the cancer foci, representing 64% of the patients, had at least one TMPRSS2-ERG positive sample." (PMID 31537872, 2019). "At odds with its homeostatic role in EC, aberrant ERG expression due to chromosomal translocations, such as the TMPRSS-2:ERG gene fusions in prostate cells, is a hallmark of cancer (reviewed in Adamo and Ladomery14)." (PMID 30892142, 2019). "In this review, aberrant splicing events in cancer-associated genes, namely BCL2L1, FAS, HRAS, CD44, Cyclin D1, CASP2, TMPRSS2-ERG, FGFR2, VEGF, AR and KLF6, will be discussed." (PMID 30463359, 2018). "For example, high GGH staining was seen in 47.2% and 44.6% of cancers with TMPRSS2: ERG fusion detected by IHC and FISH, but was found in only 32.4% of cancers without ERG staining, and in 30.6% of cancers without ERG rearrangements (p < 0.0001 each)." (PMID 28146062, 2017). "TMPRSS2:ERG expression was highest in the Bx Pos group (P = 0.013) consistent with the confirmed presence of cancer (see S4 Fig for box plot distribution of delta Ct)." (PMID 27144529, 2016). "In this study we examined potential associations between TMPRSS2:ERG gene fusion and clinicopathological characteristics with the aim of helping predict the cancer outcome." (PMID 27377958, 2016).
cancer (continued). "From these samples, we identify established driver aberrations in a cancer-related gene in nearly all cases (97.7%), including driver gene fusions (TMPRSS2:ERG), driver focal deletions (PTEN, RYBP and SHQ1) and driver amplifications (AR and MYC)." (PMID 27328849, 2016). "HOOK3 immunostaining was seen in 74.3% and 76.1% of cancers with TMPRSS2:ERG fusion detected by IHC and FISH, but found in only 38.2% of cancers without ERG staining and 44.1% of cancers without ERG rearrangements detected by FISH (p<0.0001 each)." (PMID 26230842, 2015). "Our systematic study, despite its highly preliminary nature, shows that even though it is rare, it is possible to detect TMPRSS2-ERG transcripts in cancerous prostates in areas other than the carcinoma regions." (PMID 26294063, 2015). "The tissue regions that were positively stained in ERG IHC matched the locations of carcinoma lesions, and either contained detectable TMPRSS2-ERG mRNA or were located adjacent to samples that did." (PMID 26294063, 2015). "The large number of tumors analyzed in this study enabled us to separately analyze cancer subgroups defined by molecular features, the most common of which is the TMPRSS2:ERG gene fusion." (PMID 24261794, 2013). "We previously reported a panel of TMPRSS2:ERG fusion-subtype markers for urine-based cancer detection with high specificity and sensitivity." (PMID 24133629, 2013). "Aldehyde dehydrogenase (ALDH) inhibitor disulfiram was among four cancer selective inhibitors identified blocking the growth of cultured TMPRSS2-ERG fusion positive VCaP cells at nanomolar concentration as well as reducing VCaP xenograft growth in vivo." (PMID 23251544, 2012). "Despite the disagreement concerning the role of TMPRSS2/ERG in cancer initiation, cell invasion was suggested to be a consequence of TMPRSS2/ERG fusion both in vitro and in vivo." (PMID 21747944, 2011). "Sixteen of the 24 carcinomas analyzed had FISH signal patterns indicative of a TMPRSS2-ERG rearrangement (67%)." (PMID 21814574, 2011). "We reported that deletion of the intermediate region between TMPRSS2 and ERG combined with duplication of the TMPRSS2–ERG fusion sequences is predictive of poor cancer-specific survival, an observation supported by other studies." (PMID 20104229, 2010). "In addition, PM2.5 exposure induces aryl hydrocarbon receptor (AhR)-dependent transcription of transmembrane serine protease 2 (TMPRSS2) and interleukin-18 (IL-18), further promoting cancer progression in EGFR-mutant cells." (PMID 39578555, 2025). "This indicates that while TMPRSS2 may influence immune cell infiltration, its impact on patient outcomes varies between cancer types, potentially due to differences in tumor biology and immune contexture." (PMID 40145441, 2025). "The in vitro tumor models investigated in this study showed that TMPRSS2 could enhance ACE2 expression in cancer cells, but an in depth understanding of the precise molecular pathways, through which TMPRSS2 regulates ACE2, requires further investigations." (PMID 40055791, 2025). "Therefore, a detailed exploration of ACE2 and TMPRSS2 in the context of SARS‐CoV‐2 infection is necessary to understand their impact on cancer patients." (PMID 40145441, 2025). "All sites of WA_24 were clonally related but did not share truncal mutations, indicating that the cancer, driven by a truncal TMPRSS2–ERG fusion, clonally diverged and disseminated prior to the acquisition of exonic mutations." (PMID 40824681, 2025). "The altered expression of ACE2 and TMPRSS2 in cancer patients might influence immune cell behavior within the tumor microenvironment, potentially exacerbating the severity of COVID‐19 outcomes." (PMID 40145441, 2025). "Additionally, since TMPRSS2 activity is crucial for prostate tumor cells, this structure and its high affinity also offer potential implications for cancer treatment." (PMID 39565778, 2024).